SIN3A (SIN3 transcription regulator family member A)
Diseases named in the same sentence as SIN3A in open-access papers (continued):
Sharing a sentence is not in itself a finding about the gene and the disease.
Noonan syndrome (1 paper, 2018). Noonan Syndrome (NS) is characterized by short stature, typical facial dysmorphism and congenital heart defects. "Four patients who carried LGD variants in known DD genes (POGZ, ARID1B, FOXP1, and SIN3A) and one patient who carried a known activating variant in the Noonan syndrome gene PTPN11 were considered pathogenic variants by the American College of Medical Genetics and Genomics guidelines." (PMID 30532227, 2018).
papilloma (1 paper, 2013). A benign epithelial neoplasm that projects above the surrounding epithelial surface and consists of villous or arborescent outgrowths of fibrovascular stroma. "In particular, the impaired activity of the Sin3A co-repressor complex and the concomitant overexpression of the c-Myc in HDAC1- but not HDAC2-deficient papillomas provide strong evidence for crucial function for Sin3A and HDAC1 as a negative regulator of the proto-oncogene c-Myc." (PMID 24240174, 2013).
schizophrenia (1 paper, 2014). A major psychotic disorder characterized by abnormalities in the perception or expression of reality. "SIN3A and TPM3 have also been reported to be associated with schizophrenia." (PMID 25522158, 2014).
virus infection (1 paper, 2008). "NCoR appeared associated to the IFN-β promoter before virus infection when the promoter is in a constitutively silent state, and at this stage the presence of Sin3A on the IFN-β promoter was only weakly detected." (PMID 18225953, 2008).
tumor (34 papers, 2010 to 2026). "As illustrated, Sin3A loss didn't affect tumor growth, as well as infiltrating immune cells such as CD8+ T cells." (PMID 39316363, 2024). "For example, high expression of RGS4, which was downregulated in our SIN3A knockdown gene list, has been associated with inhibition of migration, invasion and delayed tumor growth of MDA-MB-231 cells." (PMID 27780928, 2016). "SIN3A is hypothesized to control gene expression by acting as histone deacetylases, which is linked to tumor progression." (PMID 37072474, 2023). "Here, we found that Sin3a was markedly upregulated in CD44-high expressing cells by transcriptomic sequencing analysis of MMTV-MyPT tumor cells." (PMID 40409554, 2025). "Consistent with this conclusion, it has been shown that the SIN3A promotes cell survival in different cancers by forming a complex with STAT3 to silence tumor repressor genes." (PMID 38948024, 2024). "It has been shown that SIN3A inhibits cell invasion and is downregulated in cancers, thus functioning as a tumor suppressor." (PMID 38948024, 2024). "There is a possibility that SIN3A displays oncogenic or anti-tumor activity dependent on its biochemical interaction with specific protein partners, genetic interaction with other genes or regulation of target genes." (PMID 38948024, 2024). "Our results showing that knockdown of SIN3A activates autophagy and attenuates cell proliferation supports a pro-tumor activity of this epigenetic regulator." (PMID 38168833, 2024). "In vitro angiogenesis assay supported that SIN3A/3B DKO in tumor cells resulted in inhibition of HUVEC tube formation." (PMID 37655663, 2023). "The orthotopic mouse xenograft studies showed that SIN3A/3B double KO (DKO) significantly reduced MDA-MB-231 tumor growth and lung metastasis in mice." (PMID 37655663, 2023). "It has been shown to regulate proliferation and apoptosis by targeting the transcriptional regulator SIN3A, a tumor suppressor gene for NSCLC cells." (PMID 35928879, 2022). "Since LINC01279 interacts with SIN3A, its may exert pro-tumor activity through regulation of SIN3A expression." (PMID 38168833, 2024). "Given Sin3A and Sin3B share high sequence similarity, whether Sin3A has similar impact on the tumor microenvironment was evaluated." (PMID 39316363, 2024). "It has been shown that SIN3A could function as a tumor suppressor by regulating gene expression involved in cell invasion." (PMID 38948024, 2024). "According to numerous studies, SIN3a stimulates the transcription of specific target genes, while furthermore, it has been determined that SIN3a forms complexes with additional regulatory proteins to silence the transcription of several cycle-regulating and tumor-progression genes." (PMID 38275371, 2023). "In summary, our study revealed that the tumor cell-derived activated fragment C3b can be translocated into the nucleus to epigenetically regulate gene transcription by interacting with the chromatin remodeling SIN3A/HDAC complex." (PMID 37291119, 2023). "LINC00665 was validated to facilitate CRC cell growth and tumor progression via modulating miR-138-5p/SIN3A, which may offer strong evidence that LINC00665 might act as a potential therapeutic target in CRC treatment." (PMID 35101035, 2022). "Additionally, SIN3A was up-regulated in CRC tissues relative to non-tumor tissues based on results of qRT-PCR and WB analysis." (PMID 35101035, 2022). "Using Ingenuity Pathway Analysis (IPA), the top networks that were altered from these gene lists were cell death/survival, cancer, and tumor morphology for SIN3A knockdown, and cancer, cell death/survival, and organismal injury and abnormalities for SIN3B knockdown." (PMID 27780928, 2016). "Importantly, co-repressor associated deacetylase was significantly reduced for Sin3A, NuRD and Co-REST complexes in HDAC1-deficient tumours compared to wild-type tumours." (PMID 24240174, 2013). "Previous studies suggested that SIN3A could function as a tumor suppressor." (PMID 38168833, 2024).
tumor (continued). "Therefore, CHURC1 may exert tumor-suppressive effects through certain transcription factors (e.g., SIN3A) and further affect LUAD development." (PMID 36358727, 2022). "Considering that NB represent a tumor characterized by impaired neuronal differentiation, we can speculate that non-coding variants located in regulatory elements associated with both STAT3 and SIN3A transcriptional regulation could impact neuronal development." (PMID 39843641, 2025). "In this regard, it has been shown recently that the SIN3A transcriptional repressor complex interacts with STAT3 and is involved in silencing tumor repressor genes, thus promoting cell survival in different cancers." (PMID 38168833, 2024). "When examining more pro-inflammatory SIN3A*-reactive TCCs, two out of ten recognized single (TCC57) or multiple (TCC2D3) IPdBPs, demonstrating that T cells with cross-reactivity against tumours and IPdBPs can be found in the TILs." (PMID 37198490, 2023). "We predict that BPTF, SIN3A and CNOT1 enhance genomic stability and inhibit tumor cell formation by positively regulating ubiquitination in ccRCC." (PMID 33232269, 2020). "It is also clear that a number of the candidate drivers including MXI1, SIN3A, THAP1 and ATF3 are down-regulated in PRAD tumours." (PMID 28592290, 2017). "In accordance with the link between Sin3A function and c-Myc expression, we detected increased levels of c-Myc protein and the c-Myc target Skp2 in K5-SOS Hdac1Δ/Δep tumours." (PMID 24240174, 2013). "Similarly, SMI to PAH2 increased AM580’s anti-tumor efficacy, decreased metastases and improved survival in in vivo TNBC mouse models, supporting the importance of the removal of the Sin3A repressor complex." (PMID 35406744, 2022). "SIN3A and CSK both play roles in tumor suppression and their deletion may lead to an increased predisposition to and risk of neoplasia in this patient population." (PMID 22216833, 2012). "However, another report suggests that Sin3A functions as a tumor suppressor in non-small cell lung cancer (NSCLC), as down-regulation of Sin3A mRNA occurs in several cases of NSCLC." (PMID 20920219, 2010). "TIL-derived, SIN3A*-specific TCC88 served as a prototypic example to search for target antigens among sequences of all human proteins, viruses and bacteria with tropism for humans, gut microbiota, the translated proteome of the autologous primary and recurrent tumours and the tumour immunopeptidome." (PMID 37198490, 2023).
cancer (24 papers, 2010 to 2025). A tumor composed of atypical neoplastic, often pleomorphic cells that invade other tissues. "To further explore the mechanism of YAP regulation, we analyzed the ENCODE data and found that SIN3A is enriched around the YAP promoter in many cancer cell lines that are known to express YAP." (PMID 37739954, 2023). "In this review, we delineate the SIN3a-associated epigenetic mechanisms in cancer and PAH cells and highlight their impact on cell survival and proliferation." (PMID 38275371, 2023). "Research on the role of SIN3a in cancer continues to decipher the molecular complexity underlying the regulation of gene expression." (PMID 38275371, 2023). "Understanding the role and function of SIN3a may hold the key to enhanced diagnostic and therapeutic strategies, offering a beacon of hope for patients with cancer or pulmonary vascular remodeling diseases." (PMID 38275371, 2023). "SIN3a is a scaffold protein and co-repressor that plays a vital role in the maintenance of chromatin structure and regulation of gene transcription but has also been linked to aberrant gene regulation in cancer and cardiovascular diseases." (PMID 38275371, 2023). "The assembly platform for these transcriptional repressors disappears in cells expressing SIN3A p.Gln944* due to its cytoplasmic localization, indicating that transcriptional activities may be dysregulated in cancer cells carrying the mutation." (PMID 30375428, 2018). "SIN3A, a member of the SIN3 family, functions as a component of the histone deacetylase (HDAC) complex and regulates key cellular processes linked to cancer pathogenesis and progression." (PMID 38168833, 2024). "SIN3A plays an important role in cancer pathogenesis and functions as a global transcription regulator with diverse chromatin-modifying activities." (PMID 38168833, 2024). "The significance of SIN3a has received considerable attention, particularly in the field of cancer research, where its impact is broad and diverse." (PMID 38275371, 2023). "Due to SIN3a’s role in regulating epigenetic modifications, especially in cancer processes, and as many pathways underlying cancer development have been identified in PAH, SIN3a has become a key topic in PAH research." (PMID 38275371, 2023). "Switch-independent 3 family A (SIN3A) is a transcriptional regulator, that along with its paralog and corepressor play important roles in normal breast development, cancer and metastasis." (PMID 34234117, 2021). "SIN3A is downregulated in a variety of cancers and is thought to influence a specific step of tumorgenesis in part via the beta-catenin pathway." (PMID 31335867, 2019). "As another example, SIN3A is part of the SIN3A-HDAC complex that is associated with diseases including cancer, and HDAC inhibitors are known to potentiate CDDP activity, thus providing moderate but indirect evidence in favor of the reported pair SIN3A-HDAC." (PMID 31362726, 2019). "Lowered expression levels of SIN3A and SIN3B have also been associated with the progression of many cancers." (PMID 27780928, 2016). "It follows that SIN3A:BRMS1 complexes are likely regulated by the environments surrounding cancer cells." (PMID 23390556, 2013). "Although regulation of transcription by Sin3A has been studied in detail, little is understood about the function of Sin3A in cancer cells." (PMID 20920219, 2010). "Few studies have been conducted on the role of Sin3A in growth of mammalian cells, and these few reports have suggested conflicting roles for Sin3A in cancer." (PMID 20920219, 2010). "Therefore, this review aims to comprehensively explore the role of SIN3a in epigenetics, particularly in the context of cancer and PAH." (PMID 38275371, 2023). "Furthermore, we explore in detail the role of SIN3a in cancer to provide new insights into its emerging role in PAH pathogenesis." (PMID 38275371, 2023).
cancer (continued). "According to former studies, SIN3A could affect gene expression at epigenetic level, thereby affecting the progression of cancer cells." (PMID 35101035, 2022). "In recent years, emerging roles of SIN3A in cancer development have been revealed." (PMID 34884456, 2021). "Cancers displaying unfavorable risk with high ALT (BRCA, SARC, and LUAD) may be regulated by the transcriptional factors E2F4, TFDP1, E2F1, E2F7, and SIN3A (FDR = 0.001) in the DNA repair pathway, including genes repairing DNA damage such as CENPI, CLSPN, TOPBP1, and MCM4." (PMID 32784588, 2020). "As a result, many signaling pathways observed in cancer were studied in PAH and have encouraged new research studying SIN3a’s role in PAH due to its impact on cancer growth." (PMID 38275371, 2023). "FAM60A, a subunit of the SIN3A/HDAC complex, is a cell cycle regulatory protein with a key role in the division of malignant tumors." (PMID 37439040, 2023). "In addition, BPTF, SIN3A, CNOT1 and YY1 were highly positively correlated in both pan-cancer and ccRCC datasets." (PMID 33232269, 2020). "These few reports with disparate findings highlight a fundamental lack of understanding of the role of Sin3A in growth and cancer." (PMID 20920219, 2010).
infection (4 papers, 2008 to 2025). The state of being infected such as from the introduction of a foreign agent such as serum, vaccine, antigenic substance or organism. "Nevertheless, NCoR remained bound to the IFN-β promoter in ZH-infected cells while both Sin3A and NCoR were released from the promoter after C13 infection during promoter transcriptional activation." (PMID 18225953, 2008). "Notably, 12 of these TFs exhibited distinct phosphorylation patterns upon infection, including MED14, SIN3A, BCL6, cJUN, NFATC1, STAT3, RUNX3, GTF2F1, MED1, JUNB, TLE3, and FOSL2." (PMID 40368139, 2025). "Following infection, ZBTB25 and Sin3a were found to be recruited to the IL-12B promoter at 24 hpi." (PMID 33627504, 2021). "The subnuclear distribution of Sin3A observed in non-infected (a, c) and C13-infected (d, f) cells was affected after ZH-infection (g, i), Sin3A colocalizing with the NSs filament in a way similar to what we have previously observed in the case of SAP30." (PMID 18225953, 2008). "Using confocal microscopy, we analyzed the subnuclear distribution of Sin3A and NCoR in murine L929 cells either non-infected or after infection by C13 or ZH." (PMID 18225953, 2008).
SIN3A also shares sentences with these, for which no sentence is quoted: autism spectrum disorder (3 papers); Obesity (3); autism (2); colon cancer (2); melanoma (2); type 2 diabetes (2); alcoholics (1); B-cell lymphomas (1); cervical cancer (1); colorectal cancer (1); Diets-Jongmans syndrome (1); epithelial ovarian cancer (1); Ewing sarcoma (1); follicular lymphoma (1); gastric tumors (1); ichthyosis (1); invasive ductal carcinoma (1); ischemic stroke (1); liver cancer (1); medulloblastoma (1); multiple endocrine neoplasia type 2 (1); Myelodysplasia (1); myeloid leukemia (1); neurodevelopmental disorder (1); neurological diseases (1); renal clear cell carcinoma (1); systemic sclerosis (1).